MMP9 (matrix metallopeptidase 9)
Diseases named in the same sentence as MMP9 in open-access papers (continued):
Sharing a sentence is not in itself a finding about the gene and the disease.
colon carcinoma (269 papers, 2002 to 2025). "Both gelatinases (MMP-2 and MMP-9) are closely associated with cancer invasion and progression, and their elevated expression has been connected to lower survival rates among colon cancer patients." (PMID 39683504, 2024). "To further explore the association between elevated MMP‐9 expression and patient outcomes in colon cancer, we conducted an analysis of MMP‐9 expression levels alongside survival curves." (PMID 38600695, 2024). "The results from these experiments indicate that MMP‐9 depletion causes about 70% decrease in the ability of SW620 colon cancer cells to grow and expand into a colonal population." (PMID 38600695, 2024). "Adding support to this idea, we recently purified factors that can interact with MMP‐9 in SW620 colon cancer cells and detected a stable association of several sequence‐specific DNA‐binding factors (Not shown)." (PMID 38600695, 2024). "We thus concluded that MMP‐9‐dependent H3NT proteolysis is directly linked to the process of driving the expression of growth‐stimulatory genes in colon cancer cells." (PMID 38600695, 2024). "In this report, we demonstrate that the H3NT clipping activity of MMP‐9 is directly linked to altered transcription program during the development of colon cancer." (PMID 38600695, 2024). "In colon cancer, SMAD4 deficiency results in increased MMP9 expression in colon cancer cells, amplifying the expression of the hypoxia-inducible factor GLUT1, thereby promoting aerobic glycolysis processes." (PMID 38686046, 2024). "MMP9 dysregulation is often associated with poor prognosis in ovarian, breast, and colon cancer patients." (PMID 37373974, 2023). "The increasing expression of MMP9 has been reported to be associated with metastasis, and poor prognosis in breast and colon cancer." (PMID 31367490, 2019). "Our work further connects high MMP-7 and MMP-9 expression to occludin degradation, loss of tight junctions and tumor cell budding in colon cancer." (PMID 29731961, 2018). "MMP9, a gene in the family of zinc-dependent enzymes and capable of degrading various extracellular matrix components, is associated with colon cancer liver metastasis." (PMID 28109307, 2017). "In particular, MMP-2 and MMP-9 have been implicated to play a role in colon cancer progression and metastasis in animal models and patients." (PMID 27409174, 2016). "Gelatinase B/MMP-9 has also been implicated in lymphatic dissemination of colon cancer to lymph nodes." (PMID 24473089, 2014). "In addition to these observations, more recent investigations also implicated MMP‐9 in regulating distinct nuclear pathways in colon cancer cells, stressing the importance of nuclear MMP‐9 function in the process of colonic tumorigenesis." (PMID 38600695, 2024). "However, the over-expression of the MMP-9 inhibitor protein causes a change in proteolysis due to angiogenesis resulting in metastatic colon tumor invasion and inflammation." (PMID 38049552, 2023). "MMP-2 and MMP-9, known as gelatinase A and B, are critically involved in tumor invasion and metastasis and their expression has been associated with poor overall survival in patients with colon cancer." (PMID 34885656, 2021). "More recently, albeit in the setting of a murine model of colon cancer, neutrophil infiltration was most strongly associated with immunosuppression, which resulted from the release of matrix metalloproteinase 9 (MMP-9) and the resultant proteolytic activation of abundant latent TGFß in the TME." (PMID 32244751, 2020). "Additionally, the application of MMP7 to colon cancer-bearing nude mice enhanced tumour metastasis and MMP9-deficient mice were protected against tumour metastasis." (PMID 29631554, 2018). "Increased MMP-9 expression has also been shown to have an independent prognostic impact on operable non-small cell lung cancer and renal cell carcinoma, and increased IL-8 expression has been associated with worse prognostic of colon cancer." (PMID 22695075, 2012).
colon carcinoma (continued). "Inhibition of αVβ6 function using inhibitory antibodies results in total abrogation of MMP-9 activation suggesting that the expressions of αVβ6 integrin and MMP-9 are linked, and their coordinate expression appears to promote invasion by squamous and colon carcinoma cells." (PMID 19787098, 2008). "In co-culture experiments, breast and colon cancer cells exposed to platelets acquire a spindle-shaped morphology, upregulate matrix metalloproteinase-9 (MMP-9) and downregulate epithelial proteins like E-cadherin." (PMID 40514754, 2025). "We found that both MMP2 and MMP9 were significantly reduced in both colon cancer cell lines, suggesting that changes at the protein level were more pronounced than at the gene level." (PMID 41226554, 2025). "Our findings align with previous studies demonstrating significantly higher MMP-9 expression in colon cancer tissues compared to corresponding normal distal mucosa." (PMID 40729026, 2025). "It has been previously shown that MMP2 and MMP9 are upregulated by hypoxia in breast and colon cancer cells via a HIF1-dependent mechanism." (PMID 41228316, 2025). "Neutrophils suppress tumor-infiltrating T cells in colon cancer via MMP9-mediated activation of TGFβ in colon cancer." (PMID 40564191, 2025). "The results of these efforts showed that treatment with MMP‐9 inhibitor MMP9‐I for 5 days significantly impairs the process of H3NT proteolysis in colon cancer cells." (PMID 38600695, 2024). "These experiments demonstrated that MMP‐9 expression is significantly elevated in nine out of 10 colonic tumor samples and is positively correlated with the extent of H3NT proteolysis." (PMID 38600695, 2024). "Variations in MMP-9 expression were noted in the colon tumors of the CC mice in the blank and control groups (p < 0.05)." (PMID 38535948, 2024). "Our genome‐wide transcriptome analysis shows that growth‐regulatory genes are selectively targeted and activated by MMP‐9‐dependent H3NT proteolysis in colon cancer cells." (PMID 38600695, 2024). "Toward this end, we performed RNA sequencing (RNA‐seq) with total RNA isolated from control and MMP‐9‐depleted SW620 colon cancer cells." (PMID 38600695, 2024). "According to recent studies, CA inhibits MMP-9 enzymatic activity and gene expression, both of which are critical for colon cancer invasion and metastasis." (PMID 38672151, 2024). "Another significant feature of the present study is the use of CRISPR‐dCAS9 targeting system to confirm H3NT clipping‐dependent action of MMP‐9 that establish and maintain an active transcription state of growth‐stimulatory genes in colon cancer cells." (PMID 38600695, 2024). "In an effort to gain support for the MTT assay results, we also evaluated the impact of MMP‐9 knockdown on the clonogenic potential of colon cancer cells over a period of 14 days." (PMID 38600695, 2024). "If MMP‐9 induces target gene transcription by catalyzing H3NT proteolysis, it appeared plausible that artificially tethering MMP‐9 to target genes is sufficient to re‐establish an active state of transcription in MMP‐9‐depleted colon cancer cells." (PMID 38600695, 2024). "Together, these data argue strongly for the direct action of MMP‐9 on colon cancer and support the concept that MMP‐9 exerts its oncogenic function via H3NT proteolysis." (PMID 38600695, 2024). "The colon cancer-driven robust systemic inflammatory changes (involving the upregulation of MMP9) seem to induce systemic neuronal alterations and damage, which in turn have major implications regarding the development of CIPN." (PMID 39664453, 2024).
colon carcinoma (continued). "The role for MMP‐9 in colon cancer was further supported by the fact that our analysis of the leading‐edge subset in the gene set detected 20 genes encoding positive regulators of cell growth and proliferation." (PMID 38600695, 2024). "Adding support to this idea, our western blotting and RT‐qPCR detected MMP‐9 expression at much higher levels in colon cancer cells compared to normal colon cells." (PMID 38600695, 2024). "With the use of knockdown and inhibition approaches, we also confirmed a major role of MMP‐9‐dependent H3NT proteolysis in activating growth‐stimulatory genes as well as promoting colon tumor growth in vivo." (PMID 38600695, 2024). "To search for MMP‐9‐regulated genes in colon cancer cells, we analyzed the genome‐wide regulatory potential of MMP‐9 by RNA‐seq of colon cancer cells." (PMID 38600695, 2024). "For this objective, we generated xenograft models by subcutaneously injecting mock‐depleted control or MMP‐9‐depleted SW620 colon cancer cells into the right hind legs of nude mice." (PMID 38600695, 2024). "Upregulation of matrix MMP-2 and MMP-9 in carcinomas allows colon cancer cells to gain the ability to invade and metastasize." (PMID 39502780, 2024). "The injection of Cd-O2/N2 atomized gas statistically significantly suppressed the expression of MMP-9 in the colon tumors of the CC mice (C-Blank: p < 0.05)." (PMID 38535948, 2024). "MMP9 also seems to be a feasible driving factor in the development of chronic CIPN in colon cancer patients." (PMID 39664453, 2024). "Together, these initial observations link MMP‐9 to H3NT proteolysis in colon cancer cells and provide a rationale for our continued investigation in more direct fashion." (PMID 38600695, 2024). "The genome-wide transcriptome analysis showed that growth-regulatory genes are selectively targeted and activated by MMP-9-dependent H3NT proteolysis in colon cancer cells." (PMID 39409117, 2024). "The previous findings implicated matrix metalloproteinase 9 (MMP-9) as the primary protease for histone H3 N-terminal tail cleavage (H3NT) during osteoclast differentiation, melanomagenesis, and colon cancer development." (PMID 39409117, 2024). "In our initial characterization of H3NT clipping process in colon cancer cells, MMP‐9 was identified as an enzyme that mediates proteolytic cleavage of H3NT and induces abnormal cell growth." (PMID 38600695, 2024). "An apparent decrease in cell growth rate was observed upon stable depletion of MMP‐9 in SW620 colon cancer cells." (PMID 38600695, 2024). "We show that MMP‐9 is overexpressed in colon cancer cells and catalyzes H3NT proteolysis to drive transcriptional activation of growth stimulatory genes." (PMID 38600695, 2024). "Functional studies revealed that MMP‐9‐dependent H3NT proteolysis is necessary for the expression of growth stimulatory genes in colon cancer cells." (PMID 38600695, 2024). "Genistein had the potential to stop the human colon cancer cell line HCT116 from propagating because it is a potent MMP-9 inhibitor that prevents the growth and spread of tumors investigated in vivo tests in mice." (PMID 38672151, 2024). "On the other hand, MMP‐9 catalytic dead mutant failed to recover the original growth rate of MMP‐9‐depleted SW620 cells, thus suggesting that H3NT clipping activity of MMP‐9 is necessary for MMP‐9 function in promoting the growth of colon cancer cells." (PMID 38600695, 2024). "MMP‐9 knockdown and inhibition induce a rapid downregulation of target genes and diminish the growth potential of colon cancer cells." (PMID 38600695, 2024). "Here, we report that MMP‐9 is overexpressed and proteolytically cleaves H3NTs in the nuclei of colon cancer cells." (PMID 38600695, 2024). "The effect of Lut on MMP-2 and MMP-9 in the development of colon cancer was induced by azoxymethane (AOM) in BALB/c mice to investigate impacts of Lut on MMP-2 and MMP-9." (PMID 38672151, 2024).
colon carcinoma (continued). "Through the upregulation of the tumor suppressor gene KLF2, EOs from four different regions reduced the development and proliferation of colon cancer cells and the production of MMP9." (PMID 38365676, 2024). "The expression of metallothioneins and Matrix metallopeptidase 9 (MMP9) which can degrade extracellular matrix in colon cancer cells are regulated by DC-SIGNR." (PMID 38090489, 2023). "They found that KD treatment slows colon cancer progression by significantly reducing the protein expression of NF-κB 65, phosphor NF-κB p65, and MMP-9." (PMID 36831374, 2023). "MiR-7 has been reported as a regulator of MMP-2 and MMP-9 expression, acting in the invasion and proliferation of human colon cancer by directing the expression of the focal adhesion kinase." (PMID 36901866, 2023). "The overexpression of avb6 integrin was found in colon cancer, which consequently enhances MMP-9 secretion, followed by protein–kinase-c pathway activation." (PMID 37569509, 2023). "Our analyzed data showed that colon cancer patients with the high co-expression of TMEM211/MMP2 or TMEM211/MMP9 had poor DSS." (PMID 37367036, 2023). "A study inhibiting the expression of NF-κB in CT26 colon cancer cells through the overexpression of the IκB-α super-repressor found a decrease in MMP-9 expression, highlighting a link between the two." (PMID 36831374, 2023). "In colon cancer, the transcription factor c-Jun is activated by p38γ, and then recruits p38γ into the matrix metalloproteinase 9 (MMP-9) promoter leading to MMP-9 trans-activation and cell invasion." (PMID 37248432, 2023). "The survival rate was reported to significantly drop in both breast and colon cancers as a result of MMP-9 overexpression." (PMID 37569509, 2023). "Inhibits cell migration by decreasing the expression of urokinase plasminogen activator (u‐PA), tissue‐type plasminogen activator (t‐PA) and matrix metalloproteinase 9 (MMP‐9) as well as matrix metalloproteinase 2/9 (MMP‐2/9) activity in colon cancer cells." (PMID 36207986, 2023). "In this study, analysis of the Creatinine, protein carbonyl, 8-OHdG, VEGF, S.O.D., G.S.H., C.A.T., NO, MMP-9 Inhibitor, and IL-10 was carried out to investigate the nickel-induced biochemical changes in colon cancer cells." (PMID 38049552, 2023). "Recent studies have shown that protein extracts from some legume seeds, particularly the albumins from Lupinus albus, can inhibit the metalloproteinase MMP-9 involved in inflammation and cancer, as well as colon cancer cell migration." (PMID 35911116, 2022). "The TCM monomer composition (i.e., kaempferol) and target proteins MMP1 (ID : P03956), MMP2 (ID : P08253), and MMP9 (ID : P14780), which had a strong correlation with colon cancer, were screened using HERB database." (PMID 36147444, 2022). "Since the expression of MnSOD is associated with the regulation of EMT, the expression of mesenchymal markers (fibronectin, vimentin, and N-cadherin), epithelial markers (occludin and E-cadherin), and MMP-9 was examined in three colon cancer cell lines." (PMID 35883447, 2022). "In the human colorectal carcinoma cell line, SW480, CCR7 knockdown using shRNA led to reduced MMP-9 levels that, when tested in a xenograft mouse model, lowered colon cancer metastasis and increased animal survival when compared to CCR7-expressing tumor cells." (PMID 35203305, 2022).
colon carcinoma (continued). "In colon cancer, it has been suggested that neutrophils secrete MMP9, which in turn activates the inactive form of TGF-β in the microenvironment and thereby promote the inhibition of T-cells." (PMID 36438199, 2022). "Meanwhile, MMP2 and MMP9 expression in siRPL5-transfected colon cancer cells was lower than that of siNC transfection group." (PMID 36384455, 2022). "Cell-free supernatants of probiotic L. casei and L. rhamnosus GG reduced the incidence of colon cancer as well as its metastatic effects by decreasing the levels of matrix metalloproteinase-9 (MMP-9) and increasing the levels of tight junction protein ZO-1." (PMID 35054452, 2022). "Recently, the GSN level was also found elevated in colon cancer and associated with tumor invasion signaling pathways such as MMP-2/MMP-9 and the MAPK and TGF-β pathways." (PMID 35804959, 2022). "Specifically, MMP-9 is expressed in CCR7-expressing colon cancers, with a downstream response of lymph node metastasis." (PMID 35203305, 2022). "The inhibitory effects of anthocyanins on MMP-2 and MMP-9 expression were also shown in HCT-116 colon cancer cells." (PMID 35883834, 2022). "Various studies showed that SPHK1 promotes MMP2 and MMP9 expression in fibroblast‐like synoviocytes and colon carcinoma RKO cells." (PMID 34262394, 2021). "A previous study reported that PARPs activate the metastasis-related genes integrin β-1, matrix metallopeptidase-2 (MMP-2), and MMP-9 through the nuclear factor kappa-light-chain pathway in colon cancer." (PMID 34830749, 2021). "The only flour that did not interfere with the desired nutraceutical activities was buckwheat, because it showed higher bioactivity against MMP-9 activity whilst maintaining strong inhibition of colon cancer migration." (PMID 34441706, 2021). "In colon cancer, FABP4 enhances epithelial–mesenchymal transition and the associated proteins, including MMP-2, MMP-9, and E-cadherin via the AKT pathway." (PMID 34685761, 2021). "It further showed to effectively reduce MMP-9 gelatinolytic activity as well as colon cancer cell migration, hence corroborating the effectiveness of our method." (PMID 34359533, 2021). "PSVII@MCP-CaP also significantly inhibited the invasion and migration of drug-resistant colon cancer cells by increasing the expression of E-cadherin and reducing the expression of N-cadherin and MMP-9." (PMID 34789268, 2021). "The degradation of type IV collagen is found in both invasion and metastasis, and the expression of MMP-2 and MMP-9 is significantly higher in colon cancer cells." (PMID 34572476, 2021). "The Smad4 is attached to the receptor and thus regulated SMADs overwhelm colon cancer cell migration by regulating MMP-9 activity." (PMID 34096454, 2021). "For example, sevoflurane can inhibit cell migration and invasion in colon cancer cells via the ERK/MMP9 pathway by regulating miR-203." (PMID 33673181, 2021). "We explored the links between MMP2 and MMP9 expression and related immunological markers in colon cancer by TIMER." (PMID 34830271, 2021). "Platelet-secreted proteins, such as agrin and thrombin-reactive protein 1, can also enhance the activity and expression of MMP-9 through the p38MAPK pathway, thereby stimulating the aggressiveness of colon cancer." (PMID 34422629, 2021). "Sevoflurane can inhibit cell migration and invasion in colon cancer cells via the ERK/MMP9 pathway by regulating miR-203." (PMID 33919449, 2021). "Our results are consistent with it, and ELISA assays showed that astragalin inhibited cancer cells’ migration by promoting the downregulation of MMP-2 and MMP-9 expression in colon cancer cells." (PMID 33953676, 2021). "Consistent with our results, red ginseng extract has been shown to inhibit MMP2 and MMP9 expression in colon cancer cells and adipocytes." (PMID 35011007, 2021).